PLCL1 (phospholipase C like 1 (inactive))
Diseases named in the same sentence as PLCL1 in open-access papers (continued):
Sharing a sentence is not in itself a finding about the gene and the disease.
tumor (continued). "Moreover, the capacity of PLCL1 to suppress tumour progression was explored and confirmed through cell proliferation and invasion, apoptosis, xenograft and orthotopic transplantation models." (PMID 37801481, 2023). "First, PLCL1, as this protein is known to be involved in inhibition of tumor growth and metastasis." (PMID 34789839, 2022). "In addition, an interesting phenomenon of reduced tumor cell volume and the transformation of lipid droplets into small pieces in PLCL1 overexpressed cells was observed, while the cells with stable PLCL1 knockdown showed the opposite result." (PMID 31131187, 2019). "We found that the group overexpressing PLCL1 significantly inhibited tumor liver metastases." (PMID 31131187, 2019). "Statistics of lipid droplet size and cell diameter also displayed that overexpression of PLCL1 could achieve the purpose of tumor cell slimming by transforming the lipid droplets into tiny pieces, similar to the results in cells." (PMID 31131187, 2019). "Mechanistically, RUNX1 was a transcriptional suppressor of PLCL1, LCOR could interact with RUNX1 to relieve RUNX1-mediated repression of PLCL1, leading to increased PLCL1 expression, which, in turn, inhibited the tumor progression and lipid accumulation in ccRCC." (PMID 40083699, 2025). "Our study unveiled a potential molecular mechanism for the development of ccRCC, demonstrating that LCOR could interact with RUNX1 to relieve RUNX1-repressed PLCL1 transcription, leading to the upregulation of PLCL1 expression, which inhibited the tumor progression and lipid accumulation in ccRCC." (PMID 40083699, 2025). "Studies have found that peroxisome proliferative activated receptor gamma coactivator 1 alpha (PGC1α) and phospholipase C like 1 (PLCL1) mediated cellular browning by regulating uncoupling protein 1 (UCP1) level could promote tumor “slimming” and inhibit tumor progression." (PMID 37025584, 2023). "However, although the mechanism and research methods are slightly different, both findings support that PLCL1 may function as a tumour suppressor in the occurrence and progression of RCC." (PMID 37801481, 2023). "PLCL1 may promote tumor cell “slimming” by activating a reaction similar to lipid browning." (PMID 31131187, 2019). "IHC results of subcutaneous tumors also unveiled that the expression of LCOR, PLCL1 and UCP1 increased and the tumor malignant index Ki67 decreased after LCOR overexpression." (PMID 40083699, 2025). "Among the ones known to have tumor suppressive functions, we have focused on carboxypeptidase C (CPE), phosphoenolpyruvate carboxykinase 1 (PCK1), and phospholipase C-like 1 (PLCL1)." (PMID 32762776, 2020). "IHC (immunohistochemistry) staining was conducted to evaluate the expression of PLCL1 and UCP1 in a xenograft tumor, and the results were consistent with the cell results." (PMID 31131187, 2019). "Here, it is demonstrated that phospholipase C‐like 1/uncoupling protein 1 (PLCL1)/(UCP1)‐mediated lipid browning promotes tumor cell “slimming” and represses tumor progression." (PMID 31131187, 2019). "These expression alterations in PLCL1, PLCL2 and ITGB3 could could potentially influence tumor development and tumor progression." (PMID 40457272, 2025). "Furthermore, PLCL1 decreased lipid accumulation through UCP1-mediated lipid browning and facilitated tumor apoptosis by activating p38 phosphorylation." (PMID 40083699, 2025). "The COGS model includes genes such as AP1M2, PLCL1, PLCL2, ITGB3 and BSPRY, whose altered expression could contribute to tumorigenesis and tumor progression." (PMID 40457272, 2025). "Eight were selected, five upregulated and five regulated genes, and one of the DEGs, DEPP, was significantly positively correlated with PLCL1, exhibiting the highest correlation coefficient (R2 = 0.51, P < 0.001) in mRNA expression based on Pearson’s correlation of TCGA RCC tumours." (PMID 37801481, 2023).
tumor (continued). "Moreover, compared to vector tissues, HE of the PLCL1 group samples exhibited fewer areas of nuclear pleomorphism, and the results of IHC staining revealed increased LC3B and Bax expression levels and decreased levels of Ki67 compared to those in vector group tissues from the xenograft tumour model." (PMID 37801481, 2023). "A recent study revealed that PLCL1 has a critical effect on maintaining a balance between metabolism and RCC by mediating lipid metabolic gene ubiquitination levels and consuming lipids without producing adenosine triphosphate energy, inhibiting tumour growth." (PMID 37801481, 2023).
cancer (8 papers, 2015 to 2025). A tumor composed of atypical neoplastic, often pleomorphic cells that invade other tissues. "Upregulation of RGPD6, RGPD5, RGPD8, RGPD2, NUP210L, and PLCL1 has been observed in invasive tumors, implicating this functional network in the remodeling of ECM stiffness and integrin signaling, both of which enhance cancer cell migration." (PMID 40370715, 2025).
cardiovascular disease (2 papers, 2020 to 2021). "We identified one known locus (ANGPTL4) and four new loci (PLCL1, RC3H2, TMPRSS5, and LDLRAD1) associated with cardiovascular disease risk that warrant further investigation." (PMID 33186364, 2020). "This study identified one known locus (ANGPTL4) and four new loci (PLCL1, RC3H2, TMPRSS5, and LDLRAD1) associated with cardiovascular disease risk that warrant further investigation." (PMID 33186364, 2020).
PLCL1 also shares sentences with these, for which no sentence is quoted: esophageal cancer (2 papers); immune disease (2); rheumatoid arthritis (2); Allergy (1); Anxiety (1); atherosclerosis (1); celiac disease (1); Crohn disease (1); depression (1); eczema (1); gastric adenocarcinoma (1); hay fever (1); head and neck squamous cell carcinoma (1); heart diseases (1); insomnia (1); Kawasaki disease (1); language disorder (1); lung carcinoma (1); lung disease (1); metastatic disease (1); myocardial infarction (1); nephrotic syndrome (1); neurodevelopmental disorder (1); neurological disorders (1); Obesity (1); schizophrenia (1); Sjögren’s syndrome (1); sleep disorder (1); spinal tuberculosis (1); Stroke (1).
A further 2 diseases each share a sentence with PLCL1 in 1 paper.